TRIM39-RPP21 (TRIM39-RPP21 readthrough)
Synonyms: TRIM39R
Gene: Protein-coding gene on chromosome 6 (30,328,907 to 30,346,854, forward strand). Ensembl gene ENSG00000248167.
Genetic constraint (gnomAD): Loss-of-function variants: 23 observed, 63.96 expected, observed/expected ratio (o/e) 0.36, 90% interval 0.26 to 0.51. The upper end of that interval is the gene's LOEUF score, 0.51, which puts it in group 2 of 6, group 1 being the genes least tolerant of losing a copy. Missense variants: 432 observed, 661.66 expected, observed/expected ratio (o/e) 0.65, 90% interval 0.6 to 0.71. Synonymous variants: 212 observed, 253.9 expected, observed/expected ratio (o/e) 0.83, 90% interval 0.75 to 0.94.